KRTAP17-1 (keratin associated protein 17-1)
Description:
In the hair cortex, hair keratin intermediate filaments are embedded in an interfilamentous matrix, consisting of hair keratin-associated proteins (KRTAP), which are essential for the formation of a rigid and resistant hair shaft through their extensive disulfide bond cross-linking with abundant cysteine residues of hair keratins. The matrix proteins include the high-sulfur and high-glycine-tyrosine keratins.
Synonyms: KAP17.1; KRTAP16.1; KRTAP17.1
Tractability: No criterion of Open Targets' tractability assessment is met for any kind of drug.
Gene: Protein-coding gene on chromosome 17 (41,314,912 to 41,315,710, reverse strand). Ensembl gene ENSG00000186860.
Pathways (Reactome):
Developmental Biology: Keratinization
Gene Ontology:
Molecular function: protein binding
Cellular component: cytosol
Genetic constraint (gnomAD): Loss-of-function variants: 2 observed, 8.67 expected, observed/expected ratio (o/e) 0.23, 90% interval 0.093 to 0.73. That is too few expected variants to judge how well the gene tolerates losing a copy. Missense variants: 131 observed, 135.71 expected, observed/expected ratio (o/e) 0.97, 90% interval 0.84 to 1.12. Synonymous variants: 55 observed, 50.79 expected, observed/expected ratio (o/e) 1.08, 90% interval 0.87 to 1.36.
Homologues: Orthologues: chimpanzee KRTAP17-1 (100% identical), macaque KRTAP17-1 (92% identical), pig KRTAP17-1 (84% identical), rabbit KRTAP17-1 (70% identical).